KRAS (KRas proto-oncogene, GTPase)
Diseases named in the same sentence as KRAS in open-access papers (continued):
Sharing a sentence is not in itself a finding about the gene and the disease.
tumor (continued). "To further dissect HNB’s capacity to impede RAS-MAPK activation, we postulated that mutating critical residues within HNB would diminish its ability to modulate KRAS activation as well as its tumor suppressive function." (PMID 40027648, 2025). "Overall, DCLK1 promotes MAPK pathway activation via KRAS upregulation and p62 accumulation, thereby supporting tumor growth, stress adaptation, and potentially aiding intestinal epithelium regeneration after radiation injury." (PMID 40563698, 2025). "In preclinical models, KRAS G12D-specific PROTACs eliminated 95% of mutant KRAS, suppressed pERK, and showed tumor regression." (PMID 40731832, 2025). "SLC1A5 (ASCT2) is mostly upregulated, facilitating glutamine uptake to support KRAS-driven tumour growth, making it a prognostic and therapeutic biomarker." (PMID 41154605, 2025). "In the context of cancer, the WT KRAS gene also serves as a reference for normal cellular function and even acts as a tumour suppressor." (PMID 39820726, 2025). "KRAS inhibitors can also stimulate aerobic glycolysis, leading to an acidic tumour microenvironment through the secretion of lactate." (PMID 40362630, 2025). "Previously, in the context of LC, an association of mutations in the EGFR/KRAS genes and an increased expression of VEGFA/VEGFR2 in tumor tissue was demonstrated." (PMID 39940785, 2025). "The pan-KRAS inhibitors BI-2493 and BI-2865 show potent antitumor activity in vitro and in vivo in KRAS WT–amplified cell lines from this and other tumor types." (PMID 39711431, 2025). "The 3D segmentation of the tumour was manually delineated by two radiologists who were unaware of the pathological results and KRAS gene detection outcomes." (PMID 40421293, 2025). "Oncogenic KRAS signaling exerts extensive influence on glucose, lipid, and amino acid metabolism, as well as macropinocytosis in tumor cells." (PMID 40485603, 2025). "The literature data from the recent decade highlight the roles of tumour-associated mast cells, microRNAs (miRNAs), and BRAF, alongside KRAS genes, in CRC initiation and progression." (PMID 39996841, 2025). "Immunotherapy alone has demonstrated limited effectiveness, attributed to an immunosuppressive tumor microenvironment, although synergistic effects are noted when paired with KRAS-targeted agents." (PMID 40805153, 2025). "The most representative mutations in mucinous tumors are KRAS mutations and ERBB2 amplification/overexpression, which activate the MAPK signaling pathway, thereby promoting cell proliferation and tumor progression." (PMID 40427213, 2025). "Kirsten rat sarcoma viral oncogene homolog (KRAS) and GNAS mutations are frequently found in mucinous neoplasms of the pancreas and appendix, suggesting a role in tumor initiation and progression." (PMID 40319316, 2025). "The presence of KRAS mutations is supposed to affect the increased activity of VEGF, thus promoting the process of neoangiogenesis of the tumor." (PMID 40428422, 2025). "Recent studies have revealed that ADAM9 promotes tumor progression by protecting KRAS from lysosomal degradation and reducing its interaction with plasminogen activator inhibitor-1 (PAI-1) and microtubule-associated protein 1 light chain 3 (LC3)." (PMID 41383622, 2025). "KRAS-mutant tumor cells often rely on enhanced nucleotide metabolic pathways to support rapid cell proliferation." (PMID 41200180, 2025). "Tumor-derived EVs are especially rich in oncoproteins (eg, mutant KRAS, MET) and proteases (MMP2/9), which contribute to invasive and metastatic properties." (PMID 40959053, 2025).
tumor (continued). "This process is further exacerbated by KRAS mutations, which promote CXCL1 transcription and enhance MDSC mobilization into the tumor microenvironment." (PMID 40429703, 2025). "The dose of the HLA-A2/KRAS G12V-CD3 BiTE was determined with reference to that reported previously, we observed that in the presence of KRAS G12V-mutated tumor cells, the BiTE effectively activated T cells." (PMID 41472736, 2025). "The RAS/RAF/MEK/ERK and PI3K/AKT/mTOR cascades represent key signaling routes whose dysregulation contributes to tumor growth, survival, and therapeutic resistance in tumors harboring alterations such as KRAS, BRAF, PIK3CA, or PTEN." (PMID 41465387, 2025). "All of these mechanisms of action translated into excellent tumor growth inhibition effects in vivo, as observed in a panel of NSCLC xenograft models with diverse receptor density and EGFR and kRAS mutation status." (PMID 40452841, 2025). "As a tricomplex KRAS G12D-ON inhibitor, it has demonstrated robust tumor regression in preclinical models of KRAS G12D-mutant cancers, including NSCLC." (PMID 41373672, 2025). "Our analysis revealed that KRAS and BRAF mutations significantly increased the risk of tumor occurrence and death in stage II/III CRC patients." (PMID 40279317, 2025). "In colorectal and pancreatic cancers, DCLK1 overexpression suppresses tumor-suppressive miR-143/145, indirectly enhancing KRAS expression and downstream ERK/MAPK activity." (PMID 40563698, 2025). "The goal is to establish a cancer immunity cycle by promoting endogenous tumor antigen release by the generation of KRAS‐specific cytotoxic T cells." (PMID 40498983, 2025). "Garsorasib (D-1553), a highly potent and selective KRAS G12C inhibitor, has demonstrated promising anti-tumor activity and favorable safety profile in early clinical trials." (PMID 40523897, 2025). "KRAS was primarily regulated by the tumor-suppressive miRNAs let-7a-5p and miR-143-3p, which are known to control MAPK signaling pathways that influence both cell proliferation and neuronal survival." (PMID 41153395, 2025). "In pancreatic cancer, EVs carrying mutant KRAS DNA reprogram macrophages toward an M2 phenotype, enhancing immune evasion and tumor growth." (PMID 41311372, 2025). "Co-administration of the EGFR monoclonal antibody cetuximab enhances cellular sensitivity to MRTX1133, inducing tumor regression in KRAS G12D-mutant xenograft models." (PMID 40689200, 2025). "They evaluated the therapeutic potential of transferred NK cells against tumors harboring the G12D KRAS mutation in KPC mice and discovered their significant influence on delaying tumor growth." (PMID 40597785, 2025). "We observed a significant relationship between PD-L1 and HIF-1α expression, as well as between KRAS G12C mutations and HIF-1α expression in the tumor microenvironment." (PMID 39996842, 2025). "As a result, the ability of KRAS to propagate oncogenic signaling is inhibited, leading to reduced cellular proliferation and the induction of tumor cell apoptosis." (PMID 41155693, 2025). "Various recent studies have shown that changes in KRAS allelic frequencies are important both for tumor progression, as well as major biological and clinical PDAC features." (PMID 40227826, 2025).
tumor (continued). "HER2 amplification (2–5%) and RAS–MAPK pathway mutations (e.g., KRAS G12D, BRAF V600E) further drive resistance, while PI3K pathway activation via PIK3CA mutations or PTEN loss promotes tumor survival." (PMID 40733125, 2025). "QTX3034 binds to GDP-bound forms of mutant and wild-type KRAS, inhibiting KRAS signaling in vitro and inducing tumor regressions in both pancreatic and colorectal KRAS G12D xenograft models." (PMID 40361439, 2025). "Another potential way of delivering siRNA is using LNPs that carry pan-KRAS siRNA, which showed improved tumor targeting and enhanced therapeutic effects when combined with gemcitabine." (PMID 40805153, 2025). "A growing number of studies have focused on the relationship between metabolic alteration and tumor development or immune regulation in KRAS-mutant tumors." (PMID 41184283, 2025). "Very few mechanistic studies have interrogated changes in the tumor microenvironment upon KRAS inactivation or inhibition." (PMID 39782689, 2025). "The tumor‐promoting effects of Fusobacterium nucleatum were significantly stronger in KRAS G12D mutant mice compared to wild‐type mice." (PMID 40485603, 2025). "KRAS-mutant tumor cells induce activation-induced cell death (AICD) of tumor-specific cytotoxic CD8+T cells by inhibiting the NF-κB pathway." (PMID 41184283, 2025). "In mouse models, KRAS-mutant PanIN lesions show inflammation, COX2 overexpression, and early infiltration of immunosuppressive cells like T regulatory cells (Tregs), tumor-associated macrophages (TAMs), and myeloid-derived suppressor cells (MDSCs)." (PMID 40805153, 2025). "Experimental depletion of Tregs significantly improved the efficacy of KRAS G12C inhibitors combined with anti-PD-1 therapy, further enhancing the anti-tumor immune response." (PMID 40303413, 2025). "Although pleckstrin family members such as PLEK2 and CNK1 have been implicated in tumor progression through PI3K-Akt signaling and KRAS-mediated immune modulation, the role of classical PLEK (Plek1) in solid tumors remains largely unexplored." (PMID 40895569, 2025). "The whole blood circulating tumor DNA (ctDNA) gene test revealed the disappearance of the original DCTN1–ALK fusion and the concomitant emergence of a de novo KRAS amplification mutation." (PMID 41246301, 2025). "On the contrary, the restoration of wt KRAS expression in human PDAC cells with LOH significantly attenuated the malignancy of tumor cells, confirming the tumor suppressive role of the wt allele." (PMID 40227826, 2025). "Aside from tumor intrinsic effects, mutant KRAS is also known to cultivate a proinflammatory and immunosuppressive environment by causing increased levels of TGFβ and IL-10 in the TME." (PMID 40510029, 2025). "Genomic alterations, including KRAS status, high microsatellite instability (MSI) and tumor mutational burden (TMB), can significantly impact outcomes in PDAC." (PMID 41061701, 2025). "KRAS mutations can cause a sustained activation of the RAS–RAF–MAPK signalling pathway, promoting the proliferation of tumour cells and leading to an ineffective treatment with anti-EGFR monoclonal antibodies." (PMID 40421293, 2025). "This is particularly critical as resistance to KRAS inhibitors can further enhance the aggressive tumor immunosuppressive microenvironment, making the tumor even less responsive to immunotherapy." (PMID 40585984, 2025). "By demonstrating a robust and durable anti-tumor effect in "cold" tumor models, this work presents a significant advancement over existing KRAS-targeted therapies, addressing both tumor cell-intrinsic and immune-mediated resistance mechanisms." (PMID 40585984, 2025). "L-744832 demonstrated broad anticancer activity in vitro, including in KRAS-mutant cell lines, and was more effective than doxorubicin in tumor shrinkage studies." (PMID 40597785, 2025).
tumor (continued). "SMAD4 was the predominant mutation in early stages (I–II) (56.0% vs. 26.5%, p = 0.021), while later stages (III–IV) showed significantly higher rates of KRAS mutations (100.0% vs. 75.8%, p = 0.001) compared to PHC at corresponding tumor stages." (PMID 40507259, 2025). "The constitutive activation of KRAS and persistent stimulation of downstream signaling pathways drive tumor cell proliferation, migration, metastasis, and metabolic reprogramming while also enabling evasion of the antitumor immune response." (PMID 40619414, 2025). "It has been reported that KRAS signaling shapes the immunosuppressive nature of the tumor microenvironment." (PMID 40257008, 2025). "Collectively, these findings demonstrate that MSCs can serve as effective delivery vehicles for EV-associated bioPROTACs, enabling selective degradation of oncogenic KRAS in neighboring tumor cells." (PMID 41322195, 2025). "Knockout of ALDH1A1 enhanced the sensitivity of KRAS G12C tumors to both KRAS G12C and pan‐KRAS inhibitors by inducing ferroptosis in tumor cells." (PMID 40485603, 2025). "In lung adenocarcinoma, SETD2 inactivation has been validated to accelerate KRAS-driven tumor growth in murine models." (PMID 41228333, 2025). "Consistent with the cellular data, trametinib and PIK93 treatment alone slowed tumor growth in KRAS-mutant tumors, and the drug combination further inhibited tumor growth." (PMID 40055523, 2025). "Adoptive T-cell therapy (ACT) is another emerging approach that harnesses the immune system to specifically target and eliminate tumor cells expressing mutant KRAS." (PMID 40361439, 2025). "The tumor-derived exosomes from the KRAS-mutant NSCLC patients have been found to transform naïve CD4+CD25−T cells to CD4+FoxP3+ Treg-like cells, a process independent of cytokine signaling." (PMID 41184283, 2025). "Another team developed the first agonist‐based SOS1 PROTAC, which demonstrated excellent anti‐proliferative activity in various KRAS‐driven cancer cells and showed anti‐tumour efficacy in the H358 xenograft model." (PMID 40313038, 2025). "This cascade establishes a pro-immunosuppressive tumor microenvironment, ultimately contributing to immune evasion in KRAS-mutant LUAD." (PMID 40303413, 2025). "The KRAS mutation, a genetic event present in most of the PDAC cases, requires a second hit, such as the loss of tumor suppressor genes, for cancer initiation and progression." (PMID 39991930, 2025). "Invasive, oncogenic mutations in KRAS lead to persistent signaling in the MAPK pathway, which facilitates the proliferation and sustenance of the tumor." (PMID 41155343, 2025). "For instance, specific TCR-T cell therapy targeting the KRAS-G12D mutant antigen achieved promising efficacy in a patient with metastatic PC, with a 72% reduction in tumor burden six months post-treatment." (PMID 41361128, 2025). "Targeted DNA sequencing analyses of circulating tumor DNA in patients experiencing relapse have identified genetic alterations at three distinct levels that ultimately converge to reactivate KRAS signaling." (PMID 40829181, 2025). "Another study indicated that SIRT2 can also deacetylate KRAS at K147 and that its acetylation status directly regulates KRAS activity, ultimately inhibiting tumour growth and invasion." (PMID 39778006, 2025). "Experimental models showed that genetic disruption or inhibition of EGFR or ADAM17effectively blocked KRAS-induced PDAC tumour growth in vivo." (PMID 40427200, 2025). "Here, using a model of inducible and reversible expression of oncogenic KRAS in the lung, we show that the fibroblast transcriptional program directly responds to signals from tumor epithelial cells." (PMID 39782689, 2025).
tumor (continued). "For example, creatine kinase-B (CKB) has been identified as a cancer driver in KRAS-mutant CRC by promoting tumor growth and survival in hypoxia." (PMID 40361439, 2025). "Mechanistically, lactate-derived histone lactylation produced by KRAS mutant tumor cells directly activates the transcription of circATXN7, an NF-κB-interacting circular RNA." (PMID 41184283, 2025). "Inflammatory cytokines such as IL-6 and TNF-α upregulate HIF-1α and KRAS signaling, further enhancing tumor aggressiveness and resistance to therapy." (PMID 40342817, 2025). "Targeting KRAS mutations with TCR-T cell therapy offers promise, but challenges include mutation specificity, HLA restriction, tumor heterogeneity, and avoiding off-target effects on normal tissues." (PMID 40356763, 2025). "In prostate cancer, for example, the activity of the Nrf2/Keap1 system is modulated by upstream oncogenic signals, including KRAS and Myc, which influence its dual role in tumor suppression and progression depending on the cellular context." (PMID 40867898, 2025). "In a KRAS-driven murine model of NSCLC and human cell lines, STK11-mutated tumours overproduced IL6, CXCL-7, and G-CSF, known as pro-inflammatory cytokines, which determine the accumulation of neutrophils with T-cell suppressive function." (PMID 40650126, 2025). "The combination of immune checkpoint inhibitors and KRAS inhibitors has been reported to be effective in altering the tumor microenvironment." (PMID 39400496, 2025). "Conversely, NSD2 suppresses KRAS-driven pancreatic tumorigenesis by inducing the H3K36me2-dependent expression of IκBα, an inhibitor of NF-κB signaling, suggesting a putative tumor suppressive role." (PMID 41301842, 2025). "The efficacy of KRAS inhibitors is heavily contingent on contextual dependencies within the tumor microenvironment, which not only modulate initial responses but also actively drive resistance." (PMID 41170373, 2025). "KRAS can alter the phenotype of CAFs, enriching them with lipids, which promotes angiogenesis and tumor progression." (PMID 39941797, 2025). "In vitro studies with tumor cells and organoids revealed that Fusobacterium nucleatum exhibited a higher invasive ability in KRAS G12D mutant tumor cells than in KRAS G13D or wild‐type cells." (PMID 40485603, 2025). "For example, SMAD4 inhibits tumor progression initiated by KRAS (G12D) in pancreatic ductal adenocarcinomas (PDAC); in a subset of advanced tumor, intact SMAD4 promotes TGF‐β‐dependent growth and EMT." (PMID 39957375, 2025). "In summary, the biological implications of KRAS mutations in CRC are multifaceted, encompassing tumor initiation, progression, metastasis, immune evasion, and treatment resistance." (PMID 40361439, 2025). "OTUD7B, a critical modulator of mTORC2 complexes, demonstrates significant suppression of KRAS‐driven tumour growth upon knockout, providing a theoretical foundation for developing selective deubiquitinase inhibitors." (PMID 40313038, 2025). "It was shown that right‐sided tumours exhibit lower responsiveness to anti‐EGFR treatment and higher mutation rates in genes like BRAF, PIK3CA, and KRAS, suggesting potential underlying reasons for this association." (PMID 40302146, 2025). "Targeting G4s in the promoter regions of oncogenes has emerged as an appealing strategy for cancer therapy, while some KRAS G4-directed small molecules have been displayed to suppress gene expression in tumor cells." (PMID 40885393, 2025). "Next, we examined which CIC-controlled genes contribute to KRAS-driven tumor cell proliferation and drug resistance." (PMID 41219537, 2025). "Employing omics technologies and live-cell imaging, they identified that KRAS-mutant CRC cells responded markedly to biomechanical cues present in the tumor microenvironment." (PMID 40647462, 2025).